BRCA1 (BRCA1 DNA repair associated)
Diseases named in the same sentence as BRCA1 in open-access papers (continued):
Sharing a sentence is not in itself a finding about the gene and the disease.
ovarian carcinoma (continued). "Further, the evaluation of BRCA1/2 alone in tumor tissue will not identify pathogenic variants in other genes conferring hereditary ovarian cancer risk, which are found in 4–7% of women with ovarian cancer." (PMID 33030818, 2021). "Finally, up until now, most data on BRCA1/2 mutations associated with high risk for hereditary breast and ovarian cancer do not cover the North African populations." (PMID 34490083, 2021). "However, contrast-enhanced breast MRI surveillance for BRCA1/2 mutation carriers who have not developed breast and ovarian cancer is not covered by insurance; therefore, breast MRI surveillance is rarely performed." (PMID 34674065, 2021). "The expression of the m6A RNA methylation regulator in ovarian cancer patients with and without BRCA1 mutation was also analyzed, and it has been found that the expression of both FMR1 and YTHDF1 showed differences between BRCA1-mutation and non-BRCA1-mutation groups (SupportingFigure 5)." (PMID 34187307, 2021). "Thereby, the detection and monitoring of BRCA1 promoter hypermethylation may have an important impact on the clinical management of ovarian cancer patients without BRCA1 mutation." (PMID 34601813, 2021). "A study assessing CHEK2 and PALB2 mutations in high-risk Finnish BRCA1/2-founder mutation-negative breast and/or ovarian cancer individuals identified four cases of skin cancers with a co-occurring PALB2 and CHEK2 mutation, but unfortunately no details on the type of these cancers is included." (PMID 34084283, 2021). "Some clinicians may not be aware of the germline associations of specific ovarian cancer histologies and may choose to offer BRCA1 and BRCA2 testing only, even in the context of non‐serous, non‐mucinous ovarian cancer." (PMID 33369189, 2021). "BRCA1 and BRCA2 genes testing has become part of routine clinical practice in European countries and North America since the identification of the two genes in the 90’s, which greatly improved recommendations about breast and ovarian cancer risk management treatments." (PMID 34325649, 2021). "Moreover, results from Phase IIa testing of Vigil vs. placebo and recently from a Phase IIb clinical trial involving newly diagnosed advanced ovarian cancer patients with a BRCA1/2 wild-type genetic profile showed greater clinical benefit, as both relapse-free survival (RFS) and OS were improved." (PMID 34452019, 2021). "Breast and gynecological cancers, such as ovarian cancer, share common genetic and non-genetic risk factors including mutations in BRCA1 and BRCA2, the most significant risk factors for both cancers, suggesting that similar biological mechanisms drive breast and ovarian cancer development." (PMID 35011637, 2021). "We genotyped the APOBEC3A/B deletion in hospital-based samples of 1398 Norwegian epithelial ovarian cancer patients without detected BRCA1/2 germline mutations and compared to 1,918 healthy female controls, to assess the potential cancer risk associated with the deletion." (PMID 34873230, 2021). "Moreover, a loss of function in BRCA1 and BRCA2 most commonly occurs in breast and ovarian cancers." (PMID 34830749, 2021). "In the cancer cohort of 2,665 cases, we identified 74 BRCA pathogenic variants, 31 in BRCA1 with 40 carriers (2.1% in 1,880 cases) and 43 in BRCA2 with 61 carriers (2.5% in 2,417 cases), resulting in the prevalence of 3.8% in the Taiwanese cancer cohort of breast/ovarian cancer." (PMID 34235180, 2021). "Furthermore, even breast and ovarian carcinomas arising in BRCA1/2 mutation carriers do not always have LOH at the BRCA1/2 locus, and, expectedly, tumors with retention of the normal BRCA1/2 gene copy show limited sensitivity to platinum drugs." (PMID 34454564, 2021).
ovarian carcinoma (continued). "Next-generation/high throughput sequencing studies on resistant/refractory recurrent ovarian cancer tissue samples showed loss of hypermethylation I promotor region of BRCA gene and also reversions in germline BRCA1/2 mutation, which may led to higher genome stability." (PMID 34885169, 2021). "Retrospective studies have shown an improved prognosis, higher response rates to platinum-containing regimens, and longer treatment-free intervals between relapses in patients with BRCA 1 and BRCA 2 (BRCA1/2)-mutated ovarian cancer compared with patients who are not carriers of this mutation." (PMID 35582028, 2021). "Data from this study reveal that BRCA1/2 variants in the non-European population are highly specific; therefore, population-specific study is essential for clinical application of treatment or prevention for breast or ovarian cancer." (PMID 34063308, 2021). "The BRCA POC Research Assay results will also help identify patients in need of more comprehensive hereditary breast and ovarian cancer screening using affordable NGS panels for BRCA1/2 founder variant-negative patients (approximately ZAR 8000 in the state sector)." (PMID 34660253, 2021). "While current guidelines recommend germline BRCA1/2 testing for all women diagnosed with epithelial ovarian cancer, our data suggest that with appropriate validation and high technical standards, a tumor‐first testing model may be a viable option to detect both somatic and germline variants." (PMID 33030818, 2021). "An analysis of the presence of mutations in BRCA1, BRCA2, RAD51C, PALB2, and CHEK2 with the age of onset of ovarian cancer revealed a lower age of ovarian cancer diagnosis in BRCA1 mutation carriers than in non-carriers of BRCA1 (51.6 vs. 57.6, p = 2.97 × 10−11)." (PMID 33670479, 2021). "A loss of BRCA1 in mammary epithelial cells results in dedifferentiation of these cells with upregulation of CD44high/CD24low cancer stem cell (CSC) phenotype and induction of EMT However, the status of BRCA mutation and EMT remains unexplored in ovarian cancer." (PMID 34001250, 2021). "The BRCA1 mutated ovarian cell line UWB1.289 appeared to be particularly more sensitive to the cytostatic and cytocidal effects of the tested alkylating agents than the other ovarian cancer cell lines tested in consistence to its BRCAness phenotype (t-test, p < 0.001)." (PMID 34440232, 2021). "Familial ovarian cancer (OC) cases not harbouring pathogenic variants in either of the BRCA1 and BRCA2 OC-predisposing genes, which function in homologous recombination (HR) of DNA, could involve pathogenic variants in other DNA repair pathway genes." (PMID 34861889, 2021). "The purpose of this study was to develop a liquid biopsy assay that could determine the methylation status of the BRCA1 promoter to be able to monitor hypermethylation of the BRCA1 promoter and investigate its clinical significance as a predictive biomarker in ovarian cancer patients." (PMID 34601813, 2021). "In the UK, diagnostic germline genetic testing of the BRCA1/BRCA2 (hereafter BRCA1/2) genes is routinely offered through the National Health Service (NHS) to patients with a personal history (and in some cases a wider family history) of breast and/or epithelial ovarian cancer." (PMID 33654310, 2021). "Thus, indeed BRCA1/2 germline mutation related tumors do not belong to the most immune active category of breast and ovarian cancers." (PMID 32164626, 2020). "Defective DNA double-strand repair is a characteristic of germline mutations in BRCA1 and BRCA2 genes in all cells expressing them.They are also classified as pathogenic variants or deleterious mutations that predispose to familial breast and or ovarian cancer." (PMID 32102521, 2020). "Furthermore, we assessed the presence of a pathogenic variant in BRCA1/2 in first-degree relatives, of a proven carrier, who had developed endometrial cancer without previous breast or synchronous ovarian cancer." (PMID 32698099, 2020).
ovarian carcinoma (continued). "Therefore, we undertook screening of other genes in a cohort of patients with a presumed genetic predisposition for breast and ovarian cancer, in whom germline mutations in BRCA1 and BRCA2 were previously ruled out." (PMID 32756499, 2020). "Moreover, several recent clinical studies have shown that BRCA1-deficient phenotypes are found with high prevalence not only in breast and ovarian cancers, but also in pancreatic, prostatic, and other types of cancers." (PMID 33424604, 2020). "Some authors explained the contradictory results, arguing that breast and ovarian cancers have an earlier onset in BRCA1/BRCA2 mutation carriers, therefore patients might not have time to develop GC afterwards." (PMID 33198203, 2020). "In our previous work, we demonstrated that two variants in BRCA1 (c.2037delinsCC and c.3331_3334del) and one in BRCA2 (c.156_157insAlu) together represent about 50% of all deleterious variants found in Portuguese hereditary breast and ovarian cancer families mostly originated from northern Portugal." (PMID 32850417, 2020). "In addition, BRCA1/BRCA2 gene test was not covered by health insurance as a companion diagnostic test for PARP inhibitor administration for ovarian cancer in Japan, so we did not perform it in our two cases." (PMID 33300090, 2020). "In assessing association of this variant with cancer, of the 15 679 BRCA1 carriers, 7889 and 2369 carriers were affected with breast and ovarian cancers, respectively; of 10 979 BRCA2 carriers, 5605 carriers and 2369 carriers were diagnosed with breast and ovarian cancers, respectively." (PMID 32175645, 2020). "Therefore hereditary breast and ovarian cancers could be predominantly due to BRCA1/2 PVs different from those usually detected in other geographical areas of Italy and Europe." (PMID 32380732, 2020). "Comprehensive BRCA1 and BRCA2 genetic testing could, however, identify more women with pathogenic variants, thus leading to improved cancer prevention for more women at high risk of breast and ovarian cancer." (PMID 32772980, 2020). "In addition to 13.7% of deleterious germline BRCA1/BRCA2 carriers, we identified 7.4% additional patients with pathogenic germline variants in other genes predisposing for ovarian cancer, namely RAD51C, RAD51D, and MSH6, representing 35% of all pathogenic germline variants." (PMID 33008098, 2020). "Therefore, we speculated that the mutations between BRCA1 and BRCA2 synergistically lead to the occurrence of ovarian cancer in this family." (PMID 32356124, 2020). "In addition, BRCA1 promoter hypermethylation or mutational inactivation of CDK12 can downregulate transcription of BRCA1, thereby disrupting HR DNA repair in ovarian cancer, and then leading to metabolic reprogramming of ovarian cancer cells." (PMID 32570740, 2020). "An overall survival (OS) advantage was observed with olaparib for PSR ovarian cancer patients irrespective of BRCA1/2 mutation status in the updated survival data of Study19, while the median OS in BRCAmt ovarian cancer was longer than that in the BRCAwt subgroups." (PMID 32183851, 2020). "A recent study of ovarian cancer samples, from patients treated with Olaparib maintenance therapy, indicated that Olaparib also significantly improved survival outcomes in patients who lacked BRCA1/2 mutations; but harbored other DDR gene mutations." (PMID 33015058, 2020). "Hypermethylation of the BRCA1 gene resulted in its down-regulation and therefore impaired DNA repair, which again similar to BRCA1 mutations, may contribute to chromosomal or genetic instability and ultimately increase ITH in ovarian cancer." (PMID 31366178, 2019). "Although several small-size studies have previously reported the assessment of mutation profiles of susceptibility genes, there are no precise data about somatic BRCA1/2 mutations and other related known breast or ovarian cancer suppressor genes among the Chinese population with ovarian cancers." (PMID 31472684, 2019).
ovarian carcinoma (continued). "However, other studies found increased numbers of CD3- and CD8-positive TILs in BRCA1/2-mutated ovarian cancer without significant difference between BRCA1 or BRCA2 mutations." (PMID 31549213, 2019). "However, in our ovarian cancer cell lines, the efficacy of olaparib did not always corroborate with BRCA1/ 2 mutations." (PMID 30741937, 2019). "However, platinum‐resistant, BRCA1/2‐mutated ovarian cancers without secondary mutations are likely to be sensitive to PARP inhibitors." (PMID 30672100, 2019). "Four out of 10 women with BRCA1 variants carried the founder variant c.3171ins5 with an origin in Western Sweden, but if there is a correlation between this very variant and the breast and ovarian cancer ratios, is not known." (PMID 31888263, 2019). "However, the findings with respect to BRCA1 in breast and ovarian cancer raises the question whether mosaic MLH1 methylation is a risk factor for MSI positive colorectal cancer as well." (PMID 31225507, 2019). "Notably, the methylation profile across the CpG's mirrored the methylation status in healthy adults as well as ovarian cancer patients, indirectly supporting the hypothesis that BRCA1 methylation is a constitutional event." (PMID 31225507, 2019). "BRCA1 is the most highly-penetrant breast cancersusceptibility gene in breast and ovarian cancer.Detection of BRCA1 at both genomic and transcriptomiclevels is useful in breast and ovarian cancer diagnosis and itsscreening may identify individuals with a high risk of cancerdevelopment." (PMID 30124007, 2019). "Although PARPi is not yet considered as a radiosensitizer in patients with ovarian cancer harboring BRCA1/2 mutations in the clinic, the combination of radiotherapy with PARPi could provide promising synergistic therapeutic effects." (PMID 31795418, 2019). "The whole study design initialized with the determination of 752 miRNA levels in 59 samples (first stage of the study): (i) control (n = 16), (ii) ovarian cancer with no BRCA1/2 mutation (-/-) (n = 33) and (iii) ovarian cancer with BRCA1 or BRCA2 mutation (+/+) (n = 10)." (PMID 31465488, 2019). "However, the BRCA1/2 mutation prevalence is around 10% in the Ashkenazi Jewish population without a relative with a breast or ovarian carcinoma." (PMID 30713775, 2019). "Finally, we analyzed DNA from FFPE tissues of 11 index patients from families suspected of having hereditary breast and ovarian cancer, of whom no blood samples were available for testing, in order to identify underlying pathogenic germline BRCA1/2 mutations." (PMID 31029168, 2019). "Two of the nonsense mutations (p.C675X and p.E1013X) in BRCA1, 7 of the frameshift (p.N1626*11, p.N3024*16, p.Q1429*8, p.L2092*6, p.K1057*7 (x2), and p.F1546*21) in BRCA2 and a single frameshift (p.Q60*6) in PALB2 would predispose the carrier to breast/ovarian cancer." (PMID 29641532, 2018). "Importantly, BRCA1 and BRCA2 are often mutated or inactivated in spontaneous ovarian cancer." (PMID 30042330, 2018). "In kindreds carrying path_BRCA1/2 variants, testing only for the already known path_BRCA1/2 variants in the family may not be sufficient to exclude increased risk neither for BC nor for ovarian cancer or other cancers in the healthy female relatives." (PMID 29371908, 2018). "Along with BRCA1 (FANCS) and BRCA2 (FANCD1), involved in hereditary breast/ovarian cancer (HBOC) syndrome, three other members of the FANC family have been associated with an increased risk of development of BrCa and/or ovarian cancer (OvCa), namely BRIP1 (FANCJ), PALB2 (FANCN) and RAD51C (FANCO)." (PMID 29659569, 2018).
ovarian carcinoma (continued). "Olaparib (LynparzaTM), a poly(adenosine diphosphate–ribose) polymerase (PARP) inhibitor, is approved (tablet formulation) for treatment in the maintenance setting for patients with platinum-sensitive relapsed ovarian cancer, irrespective of BRCA1/2 mutation (BRCAm) status." (PMID 30353045, 2018). "Cyclin A2/E1 activation in HCC and BRCA1 inactivation in breast and ovarian cancers may thus converge towards a similar rearrangement signature, with specificities reflecting the different ways by which these genetic alterations induce replication stress or modulate response to it." (PMID 30531861, 2018). "We also examine numbers of carrier tests performed for family members of each BRCA1 and BRCA2 mutation positive identified ovarian cancer patient, as prevention efforts rely on uptake of carrier testing in family members who have yet to be diagnosed with ovarian cancer." (PMID 29506471, 2018). "Population panel testing for BRCA1/BRCA2/RAD51C/RAD51D/BRIP1/PALB2 gene mutations is the most cost-effective genetic-testing strategy in general-population women and can prevent thousands more breast and ovarian cancers than current clinical-criteria based approaches." (PMID 30400647, 2018). "The tendency of older age of onset for ovarian cancer in BRCA1/2 mutation carriers could not be confirmed statistically because the number of cases with ovarian cancer was too low." (PMID 29176636, 2018). "Our literature search shows that variation in the prevalence of high-penetrance alleles in genes such as BRCA1 and BRCA2 may contribute to the reported differences in breast and ovarian cancer incidence across India, in Indians in other countries, and between India and the west." (PMID 35693198, 2018). "Examination of the sensitivity, specificity, accuracy and MCC for a set of BRCA1 and BRCA2 mutations alone sheds little light on the amounts of patients that would be affected by misleading findings in a clinical setting, e.g., genetic testing in families at risk for breast and ovarian cancer." (PMID 29580235, 2018). "Therefore, the road towards the development of a consensus guideline on the BRCA1/2 testing should be fully covered quickly and facilitated through close cooperation between experts in the field of ovarian cancer specialists, pathologists, molecular biologists, and clinical-molecular geneticists." (PMID 29731958, 2018). "Biological relatives share an even greater proportion of their genetic code, so a particular BRCA1 mutation, for example, may not identify an individual but rather a group of related individuals who have a family history of breast and ovarian cancer." (PMID 29622529, 2018). "Additionally, we used the Oncomine®BRCA1/2 Panel to detect germline mutations and copy number alterations in randomly-selected patients with breast and/or ovarian cancer, and compared our findings with the sequencing results of the Ion AmpliSeqTM BRCA1/2 Panel." (PMID 29383094, 2017). "Genetic factors predisposing to breast and ovarian cancer primarily remain unknown in HBOC families negative for BRCA1 and BRCA2 mutations." (PMID 28738860, 2017). "Improvement of OC screening strategies in high risk women is urgently warranted not only for BRCA1 mutation carriers who decide to postpone or forego RRSO, but also for women with a family history who should follow early detection programs for breast and ovarian cancer." (PMID 29244844, 2017). "In our previous study, we demonstrated that mutations of eight members of the ADAMTS family (including ADAMTS16 gene) were significantly associated with chemotherapy sensitivity and longer survival in patients with ovarian cancer, independent of BRCA1 or BRCA2 mutations." (PMID 29179445, 2017). "However, the joint predictive power of miRNAs and lncRNAs in prognosis for ovarian cancer (OV) patients with wild-type BRCA1/2 is as yet unknown." (PMID 28978132, 2017).